NR1I3 (nuclear receptor subfamily 1 group I member 3)
Description:
Binds and transactivates the retinoic acid response elements that control expression of the retinoic acid receptor beta 2 and alcohol dehydrogenase 3 genes. Transactivates both the phenobarbital responsive element module of the human CYP2B6 gene and the CYP3A4 xenobiotic response element.
Synonyms: CAR; MB67; CAR1
Tractability: Small molecule: a structure with a bound ligand is known; a high-quality ligand is known; it has a binding pocket of medium quality; it belongs to a druggable protein family. PROTAC: a small molecule that binds it is known.
Target class: Transcription factor; Nuclear hormone receptor subfamily 1 group I; Nuclear receptor; Nuclear hormone receptor subfamily 1; Nuclear hormone receptor subfamily 1 group I member 3
Safety:
Unwanted effects reported when the protein is acted on. In parentheses: how it was acted on, where the effect was seen, and who reports it.
Increase, hepatocellular adenomas and carcinomas (activation; source: AOP-Wiki)
Increased, Liver Steatosis (inhibition; source: AOP-Wiki)
Loss, Cochlear function (activation; source: AOP-Wiki)
anemia (source: ClinPGx)
neutropenia (source: ClinPGx)
Gene: Protein-coding gene on chromosome 1 (161,229,666 to 161,238,262, reverse strand). Ensembl gene ENSG00000143257.
Subcellular location: Nucleus; Cytoplasm; Cytoplasm, cytoskeleton
Subcellular location (Human Protein Atlas): Nucleoplasm
Pathways (Reactome):
Gene expression (Transcription): Nuclear Receptor transcription pathway
Gene Ontology:
Molecular function: DNA-binding transcription activator activity, RNA polymerase II-specific; nuclear receptor activity; protein binding; RNA polymerase II transcription regulatory region sequence-specific DNA binding; sequence-specific double-stranded DNA binding; DNA-binding transcription factor activity; DNA-binding transcription factor activity, RNA polymerase II-specific; RNA polymerase II cis-regulatory region sequence-specific DNA binding; DNA binding; sequence-specific DNA binding; zinc ion binding
Biological process: positive regulation of transcription by RNA polymerase II; cell differentiation; intracellular receptor signaling pathway; negative regulation of transcription by RNA polymerase II; signal transduction; osteoblast differentiation; regulation of DNA-templated transcription
Cellular component: nucleoplasm; chromatin; cytoplasm; nucleus; cytoskeleton
Genetic constraint (gnomAD): Loss-of-function variants: 33 observed, 43.49 expected, observed/expected ratio (o/e) 0.76, 90% interval 0.57 to 1.01. The upper end of that interval is the gene's LOEUF score, 1.01, which puts it in group 4 of 6, group 1 being the genes least tolerant of losing a copy. Missense variants: 388 observed, 454.46 expected, observed/expected ratio (o/e) 0.85, 90% interval 0.79 to 0.93. Synonymous variants: 143 observed, 175.01 expected, observed/expected ratio (o/e) 0.82, 90% interval 0.71 to 0.94.
Homologues: Orthologues: chimpanzee NR1I3 (99% identical), macaque NR1I3 (97% identical), dog NR1I3 (85% identical), pig NR1I3 (84% identical), guinea pig NR1I3 (80% identical), rat Nr1i3 (79% identical), rabbit NR1I3 (76% identical), mouse Nr1i3 (75% identical), tropical clawed frog nr1i3 (48% identical), zebrafish nr1h5 (26% identical), zebrafish rarab (26% identical), zebrafish raraa (26% identical), and 183 more. Paralogues in human: NR1I2 (46% identical), VDR (40% identical), NR1H3 (32% identical), NR1H2 (32% identical), NR1H4 (30% identical), THRB (30% identical), THRA (28% identical), NR1D1 (26% identical), NR1D2 (26% identical), PPARA (26% identical), RARA (26% identical), PPARD (25% identical), and 6 more.
Diseases named in the same sentence as NR1I3 in open-access papers:
NR1I3 is named in the same sentence as 55 diseases in open-access papers, as found by Europe PMC text mining. Sharing a sentence is not in itself a finding about the gene and the disease. The quoted sentences say what the papers report.
Hepatic steatosis (8 papers, 2011 to 2022). Steatosis is a term used to denote lipid accumulation within hepatocytes. "In mouse models on a HFD, NDL PCBs, e.g. Aroclor 1260, increased diet-induced hepatic steatosis, inflammation and fibrosis by affecting pathways regulated by epidermal growth factor receptor, constitutive androstane receptor (CAR, Nr1i3) and Pregnane X receptor (PXR, Nr1i2)." (PMID 34548932, 2021).
Kleefstra syndrome (6 papers, 2014 to 2022). A genetic disorder characterized by intellectual disability, childhood hypotonia, severe expressive speech delay and a distinctive facial appearance with a spectrum of additional clinical features. "This work strengthened NR1I3 as the gene underlying the Kleefstra-syndrome-like phenotype in this specific patient, and enabled the genetic diagnosis of all four investigated patients." (PMID 31088981, 2019). "In humans, a genetic association study identified a mutation of CAR (NR1I3) in a cohort of pediatric subjects affected by the Kleefstra syndrome (KS) (OMIM#610253), a condition characterized by neurodevelopmental delay, dysmorphic features, behavioral and intellectual disabilities." (PMID 33171992, 2020). "In addition, pathogenic de novo variants in MBD5 and in other epigenetic regulators (SMARCB1, NR1I3, KMT2C) were reported in individuals with a clinical diagnosis of Kleefstra syndrome (KS; OMIM #610253)." (PMID 35205380, 2022). "In addition to EHMT1 mutations, de novo variants were reported in four additional genes (MBD5, SMARCB1, NR1I3, and KMT2C), in single individuals with clinical characteristics overlapping Kleefstra syndrome." (PMID 29069077, 2017). "In a cohort of patients with Kleefstra-syndrome-like appearance but no EHMT1 mutations, next-generation sequencing approaches revealed single de novo mutations in five novel candidate genes (MBD5, SMARCB1, KMT2C, NR1I3 and MTMR9) in four patients." (PMID 31088981, 2019).
Obesity (6 papers, 2011 to 2023). Accumulation of substantial excess body fat. "Although NR1I2 and NR1I3 are xenobiotic receptors investigated in cancer, drug interaction, obesity, and metabolic diseases, in the present study we infer a potential connectivity with many of the MRDT chemicals." (PMID 26662846, 2016).
breast cancer (5 papers, 2016 to 2024). A primary or metastatic malignant neoplasm involving the breast. "NR1I3 is up-regulated in all mammary-tumor sub-types, with the sole exception of Normal-like cancer." (PMID 26894976, 2016). "Third, for the NR1I3 gene, another SNV has been reported to be protective against CIPN33 in a small study of CIPN and genes related to absorption, distribution, metabolism, and excretion of drugs in breast cancer patients." (PMID 38755266, 2024). "There are no studies on NR1I3 in breast cancer indicating whether it could be oncogenic or not." (PMID 26894976, 2016).
colitis (4 papers, 2022 to 2024). Inflammation of the colon. "Several nuclear receptors were specifically downregulated in males (Vdr, Lrh1/Nr5a2, Mr/Nr3c2, Rev-erbβ/Nr1d2, Car/Nr1i3, Esrrg, Lxrα/Nr1h3) and have indeed been demonstrated to regulate key protective functions relating to colitis or CRC." (PMID 36142324, 2022). "By comparing colonic mRNA levels of various BARs in colitis animals, most BARs levels were increased in PCDSS mice, such as Gpbar1(TGR5), Vdr, Nr1h3 (LXRα), Nr1h2 (LXRβ), Nr1i2 (PXR), and Nr1i3 (CAR)." (PMID 36050867, 2022).
hepatocellular carcinoma (3 papers, 2016 to 2023). A malignant tumor that arises from hepatocytes. "Furthermore, we found significant differences in clinicopathological characteristics (age, gender, fibrosis Ishak score, pathologic T, and race) between HSPA1A, NR1I3, PPARGC1A, and MAT1A gene expressions and hepatocellular carcinoma patients." (PMID 37993485, 2023).
liver cancer (3 papers, 2018 to 2025). An epithelial or non-epithelial malignant neoplasm that arises from the liver. "More importantly, when analyzing motifs over-represented in cancers relative to inflamed livers, we identified the DNA binding site for CAR (Nr1i3, belonging to the NR1 family of Thyroid hormone receptor-related factors), which is also overexpressed in Mdr2-/- liver cancers." (PMID 29734330, 2018).
AIDS (2 papers, 2012 to 2015). A syndrome resulting from the acquired deficiency of cellular immunity caused by the human immunodeficiency virus (HIV). "Targeted sequencing of the DBDs in NR1I2 [GenBank: AF364606] and NR1I3 [GenBank: BC069626.1] in 32 HIV/AIDS patients identified a total of 13 genetic variants." (PMID 23173844, 2012). "This study aimed to further contribute to the genetic characterization of African populations by genotyping NR1I2 and NR1I3 and evaluating the effects of their variants on the response to efavirenz treatment in HIV/AIDS Bantu-speaking South African patients." (PMID 23173844, 2012). "Genetic variation in CYP2A6, NR1I3 (coding for constitutive androstane receptor-CAR), and UGT2B7 has also been shown to be associated with significantly elevated efavirenz concentrations among HIV/AIDS patients." (PMID 26402689, 2015). "This study investigated variation in NR1I2 and NR1I3 and its effect on plasma efavirenz levels in HIV/AIDS patients." (PMID 23173844, 2012).
alcoholic liver diseases (1 paper, 2025). A disorder caused by damage to the liver parenchyma due to alcohol consumption. "In alcoholic liver disease, while Nr1i3 transcription remains unaffected, both basal and phenobarbital-induced nuclear translocation of CAR are impaired, leading to elevated serum bilirubin levels." (PMID 40904458, 2025).
colon cancer (1 paper, 2024). "We designed in vitro experiments to test if L. gasseri ATCC33323 can regulate E-cadherin through NR1I3 and validated these findings in the colon cancer cell lines Caco2 and HCT116." (PMID 39250508, 2024).
depression (1 paper, 2017). "Both mRNA expression of Nr1i3 and protein expression of CAR were consistently up-regulated in depression model rats in this study." (PMID 28574832, 2017).
gastritis (1 paper, 2024). Inflammation of the stomach. "In gastritis, the co-expressed genes NR1I3, NR6A1, and NR0B2 are associated with anti-inflammatory steroid hormone synthesis and metabolism." (PMID 39336801, 2024).
Hypertension (1 paper, 2016). The presence of chronic increased pressure in the systemic arterial system. "Many reports showed that CETP, LIPC and LIPG were associated with HDL and LDL and that MTHRR had known main effects for LDL and blood pressure, NR1I3 for lipid metabolism, PLTP for LDL, FOXO1 for LDL and hypertension, SMAD9 for hypertension, and CSMD1 for SBP." (PMID 27104857, 2016).
liver failure (1 paper, 2025). A liver disease characterized by the liver losing or has lost all of its function. "Additionally, impaired induction of NR1I3 (CAR) is associated with liver failure following excessive tissue loss as well." (PMID 40006040, 2025).
liver fibrosis (1 paper, 2025). "In our GSEA single-gene enrichment results, the genes associated with the oxidative phosphorylation pathway are downregulated alongside the lower expression of NR1I3 under advanced liver fibrosis conditions." (PMID 40006040, 2025). "Although there is no direct evidence supporting the relationship between the suppression of NR1I3 and advanced liver fibrosis, NR1I3 remains a promising target for the treatment of liver fibrosis." (PMID 40006040, 2025). "The univariate logistic regression analysis indicates that the three hub genes affect the occurrence of liver fibrosis, as follows: CDKN1A with an odds ratio (OR) of 1.22 (95% CI: 1.08–1.39), NR1I3 with an OR of 0.92 (95% CI: 0.87–0.89), and TUBB1 with an OR of 0.95 (95% CI: 0.80–1.16)." (PMID 40006040, 2025).
Sepsis (1 paper, 2025). Sepsis is defined as life-threatening organ dysfunction caused by a dysregulated host response to infection. "In conclusion, these findings suggest that the loss of HNF4α and PPARα function during sepsis disrupts Nr1i3 transcription, thereby impairing CAR activity." (PMID 40904458, 2025). "Consequently, these findings indicate that the loss of HNF4α function during sepsis not only decreases Nr1i3 mRNA expression, but also reduces chromatin accessibility at CAR binding sites, thereby contributing to its impaired DNA binding in CLP." (PMID 40904458, 2025). "NCT prevented the reduction of HNF4α binding to the Nr1i3 promoter following sepsis, as assessed by ChIP-qPCR, thereby enhancing its transcription in the liver during CLP." (PMID 40904458, 2025). "Reduced HNF4α binding to the Nr1i3 promoter and diminished Ppara expression has been observed in the liver during sepsis, which both contributed to the downregulation of Nr1i3 mRNA, as found in this study." (PMID 40904458, 2025). "An interesting nuclear receptor, whose expression is mainly regulated by HNF4α and has barely been investigated in sepsis, is the constitutive androstane receptor (CAR), encoded by the Nr1i3 gene." (PMID 40904458, 2025). "Furthermore, since Nr1i3 mRNA expression levels are reduced in sepsis, compromising responsiveness to TCPOBOP, targeting upstream of CAR, as demonstrated with NCT, seems more rational." (PMID 40904458, 2025). "To investigate the mechanism responsible for the reduced CAR transcriptional activity during sepsis, we first examined whether Nr1i3 mRNA expression was affected." (PMID 40904458, 2025). "We conclude that Nr1i3 mRNA expression is decreased and CAR DNA binding is impaired, thereby reducing its transcriptional activity in the liver during sepsis." (PMID 40904458, 2025). "Like in mouse sepsis, Nr1i3 and all CAR target genes investigated were downregulated in pig sepsis, although the downregulation was generally less pronounced in pigs than in mice, except for NR1I3 and the CYP genes." (PMID 40904458, 2025). "Furthermore, since several CAR target genes, including Cyp2b10, correlated with lethality, hepatic CAR activity, or hepatic Nr1i3 or Cyp2b10 mRNA expression, could be explored as biomarkers in sepsis in the future, with plasma bilirubin and bile acid levels as potential surrogates." (PMID 40904458, 2025). "In that regard, activating HNF4α to enhance Nr1i3 transcription and CAR activity may be a more beneficial therapeutic approach in sepsis." (PMID 40904458, 2025).
tumor (8 papers, 2018 to 2025). "NR1I3 regulates a set of genes involved in cellular growth, and studies have shown that it may also aid in the promotion of tumor formation." (PMID 31851620, 2019). "The Constitutive Androstane Receptor (CAR) (NR1I3) is among the leading members of the xenosensor family, and it is involved in the modulation of physiologic and pathophysiological conditions through the regulation of cell proliferation, energy homeostasis and tumor development." (PMID 40255499, 2025). "Further, we employed SCENIC to predict transcription patterns of tumor cells, finding a series of key TFs of HCC tumorigenesis, such as TFs in regulation of cell dedifferentiation (SPI1, HMGB3, and YBX1) and in abnormal bile acid metabolism (NR1H4, NR1I3, FOXA3 and DDIT3)." (PMID 37985711, 2023).
NR1I3 also shares sentences with these, for which no sentence is quoted: cancer (10 papers); cholestasis (6); steatosis (5); liver disease (4); metabolic disease (3); diabetes (2); endocrine disorders (2); epilepsy (2); hepatocellular adenoma (2); Hyperglycemia (2); alcohol fatty liver disease (1); atherosclerosis (1); autism (1); brain tumour (1); cholangiocarcinoma (1); Cholestatic liver disease (1); Cirrhosis (1); colon adenocarcinoma (1); colorectal adenocarcinoma (1); colorectal cancer (1); dementia (1); endometriosis (1); endothelial dysfunction (1); glioblastoma (1); GNE myopathy (1); Hyperbilirubinemia (1); inflammatory bowel disease (1); insomnia (1); Insulin resistance (1); intellectual disabilities (1).
A further 8 diseases each share a sentence with NR1I3 in 1 paper.